ATG5 (autophagy related 5)
Diseases named in the same sentence as ATG5 in open-access papers (continued):
Sharing a sentence is not in itself a finding about the gene and the disease.
cardiomyopathy (14 papers, 2013 to 2025). A disease of the heart muscle or myocardium proper. "First, we showed that high phosphate exacerbates cardiac phenotypes in atg5-deficient mice, suggesting that high phosphate induces cardiomyopathy through an atg5-independent pathway." (PMID 33915953, 2021). "Cardiac specific loss of autophagy through a genetic deficiency of autophagy-related 5 (Atg5) was shown to cause cardiomyopathy, LV dilatation, and contractile dysfunction." (PMID 29872406, 2018). "Deletion of ATG5, the gene encoding a protein that regulates phagophore expansion, is known to result in cardiomyopathy in mice." (PMID 26301254, 2015). "Global loss of autophagy, as in the case of the Atg5-null mouse, results in cardiomyopathy and heart failure." (PMID 23737997, 2013). "In mice, Atg5-deficiency causes cardiomyopathy associated with progressive aging." (PMID 35880107, 2022). "Finally, to test the model of tandem events of phosphate loading–decreased autophagy–cardiac remodeling, we examined for additive effects of high dietary phosphate and myocardial atg5 deficiency on cardiomyopathy." (PMID 33915953, 2021). "For example, cardiac Atg5 knockout mice develop a cardiomyopathy characterized by hypertrophy, fibrosis and reduced fractional shortening, compared to wild-type mice, leading to a low median life span of 1 year." (PMID 40068328, 2025). "In mice, ATG7−/− or ATG5−/− leads to cardiomyopathy characterized by inhibited autophagy and induced mesenchymal transition and apoptosis." (PMID 36939901, 2023). "The Atg5−/− mice showed a disorganized sarcomere structure and collapsed mitochondria in cardiac tissue, leading to the development of a cardiomyopathy phenotype and systolic dysfunction in aged animals." (PMID 37623365, 2023). "In contrast, inhibiting autophagy by cardiomyocyte-specific deletion of autophagy-related 5 (Atg5) leads to cardiomyopathy in adult mice." (PMID 35682624, 2022). "Mice with a conditional deletion of atg5 in cardiomyocytes have a shorter lifespan, higher level of apoptosis in cardiomyocytes, severe cardiomyopathy characterized by cardiac dysfunction, hypertrophy, and fibrosis." (PMID 33915953, 2021). "Furthermore, cardiac-specific ablation of Atg5, critical for autophagy function, causes heart failure in aged mice, whereas the accumulation of misfolded mutant cardiac Myosin binding protein-C (cMyBP-C) impairs protein homeostasis and causes cardiomyopathies in mice and humans." (PMID 26840306, 2016). "Deletion of ATG5, which is essential for autophagy, results in cardiomyopathy in mice." (PMID 26301254, 2015). "It’s known that Atg5 and Beclin1 both are related with autophagosome formation, but Beclin1 can induce autophagy independent of Atg5 indicating a complicated function in cardiomyopathy." (PMID 35534453, 2022).
colitis (14 papers, 2019 to 2025). Inflammation of the colon. "Mice with conditional knockout of Atg5 in IECs (Atg5flox/flox/villin-Cre mice) were subjected to dextran sulfate sodium (DSS)-induced colitis and analyzed for colitis susceptibility." (PMID 31703091, 2019). "To investigate the effect of Atg5 deficiency in IECs on colitis, we prepared DSS colitis models using WT, Atg5flox/+/villin-Cre, and Atg5flox/flox/villin-Cre mice." (PMID 31703091, 2019). "We found that ATG5/7/12 mRNA levels increased in mice with colitis, and that ANP prevented this increase." (PMID 35280696, 2022). "In parallel, the inhibition of ATG5 exacerbated LPS-induced inflammation, while the administration of autophagy stimulators reduced the severity of experimental colitis in mice." (PMID 33652555, 2021). "In the same vein, in DSS-induced mice, treatment with curcumin-enriched polyphenolics ameliorated colitis by impeding excessive autophagy and reducing the mRNA and protein expression of autophagy-related 5, LC3-phosphatidylethanolamine conjugate, and beclin-1 in colonic tissue." (PMID 40359212, 2025). "Besides elevating the LC3-II/LC3-I ratio, ATG5 and Beclin-1 levels and decreasing P62 level, the ANI/NEO combination decreased the expression of several inflammatory cytokines (INF-γ, TNF-α, IL-6, and IL-22) in colon tissue from mice with DSS-induced colitis." (PMID 38354108, 2024). "In myeloid cells, the absence of ATG5 will shunt selective autophagy receptor NBR1 to target IL-12 to late endosomes for secretion, thus instigating inflammation in a murine colitis model." (PMID 37425656, 2022).
Parkinson disease (13 papers, 2008 to 2025). A progressive degenerative disorder of the central nervous system characterized by loss of dopamine producing neurons in the substantia nigra and the presence of Lewy bodies in the substantia nigra and locus coeruleus. "For instance, a correlation of plasma ATG5 level with cognition impairment has been found in patients with Parkinson's disease." (PMID 38511768, 2024). "MiR-30c-5p regulates the progression of Parkinson’s disease through attenuating ATG5-inhibited apoptosis and -induced autophagy." (PMID 34113238, 2021). "Knock-down of atg5 caused an upregulation of β-syn, (β synuclein), PINK1 (PTEN induced kinase 1) and parkin proteins, which have been related to Parkinson’s disease." (PMID 33917666, 2021). "In fact, SNPs in ATG5 and ATG7 are linked to the development of neurological disorders such as cerebral palsy (both ATG5 and ATG7), Huntington’s disease (ATG7), and Parkinson’s disease or spinocerebellar ataxia (ATG5)." (PMID 33147747, 2020). "Finally, in a zebrafish model of Parkinson’s disease, depleted atg5 expression was shown to aggravate the Parkinson’s disease phenotype, with a further reduction in the number of dopaminergic neurons and a worsening of locomotor behavior." (PMID 33917666, 2021). "siRNA-mediated knockdown (KD) of a modulator for autophagosome formation, ATG5, BECN1, or FIP200 inhibited autophagic flux and secretion, causing accumulation of Triton X-100-insoluble α-synuclein (α-syn), which is an aggregate-prone protein responsible for neuronal loss in Parkinson’s disease." (PMID 40683447, 2025). "CGA also modulated the expression of genes related to Parkinson’s disease and autophagy, including α-synuclein (α-syn), LC3B, SQSTM1, ATG5, ATG7, and ULK1B, thereby indicating its capacity to enhance autophagy in Parkinson’s disease pathogenesis." (PMID 41142236, 2025). "Mitochondrial spheroid likely acts as an alternative mitochondrial quality control mechanism independent of autophagy-related 5 (ATG5) and ATG7 but is negatively regulated by Parkin, a Parkinson disease-related E3 ubiquitin ligase." (PMID 39872017, 2023).
Sepsis (13 papers, 2016 to 2024). Sepsis is defined as life-threatening organ dysfunction caused by a dysregulated host response to infection. "In this present study, we provide evidence showing a significant association of ATG5 promoter polymorphisms with predisposition to sepsis progression in a Chinese Han population." (PMID 28839236, 2017). "And this present study indicated a significant association of ATG5 promoter polymorphisms with the progression of sepsis that the rs510432 A and rs506027 C alleles were both overrepresented among the severity of sepsis." (PMID 28839236, 2017). "Our results showed that ATG5 expression levels decreased with the severity of sepsis, and rs506027 T > C and rs510432 G > A were associated with sepsis progression and mortality." (PMID 28839236, 2017). "In this present study, five polymorphisms of ATG5/ATG16L1 were investigated for the possible risk on sepsis in a Chinese Han population." (PMID 28839236, 2017). "The genotype frequencies of the ATG5 promoter polymorphisms (rs510432 and rs506027) in the mild sepsis subgroup significantly differed from those in the severe sepsis subgroup (P = 0.013) and in the septic shock subgroup (P = 0.043)." (PMID 28839236, 2017). "Given the evidence implicating significant roles of the autophagy protein ATG5 in the inflammatory response during sepsis, we further evaluated the possible associations between these genetic polymorphisms and the production of these related cytokines in sepsis patients." (PMID 28839236, 2017). "Taken together, these results above indicated that these two ATG5 promoter polymorphisms may be functional and clinically significant for sepsis progression, underscoring its potentially therapeutic implications for sepsis and other inflammatory diseases." (PMID 28839236, 2017). "In conclusion, these results indicate that the upregulation of Atg5 expression is a crucial factor in the protective effect of BRD3308 on sepsis-induced ALI." (PMID 39224841, 2024). "The results showed that sepsis miR-506-3p OE group had significantly decreased expressions of PIK3CA, PI3K and mTOR (p < 0.01), and significantly increased expressions of Beclin, LC-3II and ATG5 compared with sepsis miR-506-3p OE NC group (p < 0.01)." (PMID 37285838, 2023). "In the present study, the levels of calpain 1 and cleaved Atg5 and the phosphorylation/activity of mTOR were significantly increased in the livers of mice with sepsis." (PMID 30154452, 2018). "The genotype/allele frequency distributions of ATG5 and ATG16L1 polymorphisms in two subgroups stratified by 28-day mortality of sepsis patients were further evaluated." (PMID 28839236, 2017). "We then explored the possible associations of these genetic polymorphisms of ATG5 and ATG16L1 with the occurrence of sepsis." (PMID 28839236, 2017). "The sepsis patients bearing the ATG5 rs510432 GA/AA and rs506027 TC/CC genotypes exhibited significantly lower expression of ATG5 compared to the rs510432 GG and rs506027 TT genotype carriers (Both P = 0.009)." (PMID 28839236, 2017). "These lines of evidence demonstrate that ATG5 and ATG16L1, which have been implicated in autophagy initiation and regulation, play a significant role in the pathogenic mechanism underlying the development of sepsis." (PMID 28839236, 2017). "In this hospital-based case-control study, we investigate the clinical relevance of three ATG5 polymorphisms (rs510432, rs506027 and rs548234) and two ATG16L1 polymorphisms (rs10210302 and rs2241880) for susceptibility to and progression of sepsis in a Chinese Han population." (PMID 28839236, 2017). "Deletion of the genes that encode autophagy-related proteins, such as autophagy-related gene-5 (Atg-5), exacerbates the production of pro-inflammatory cytokines in multiple tissues following sepsis, suggesting increased autophagy is a compensatory response that limits sepsis-induced tissue damage." (PMID 34711216, 2021).
Sepsis (continued). "To evaluate whether three ATG5 polymorphisms (rs510432, rs506027 and rs548234) and two ATG16L1 polymorphisms (rs10210302 and rs2241880) were associated with sepsis progression, we separated the cases into mild sepsis, severe sepsis and septic shock subgroups on the basis of sepsis severity." (PMID 28839236, 2017). "When discussing the autophagy process in sepsis, LC3I/II, Beclin, and ATG5 are three commonly-mentioned autophagy-related proteins that play an important role in the autophagy pathway." (PMID 38784395, 2024). "In the GSE57065 control and sepsis groups, ATG5 (autophagy-related 5), and GBP5 (guanylate-binding protein 5) had degree 19 and 25, respectively." (PMID 33667236, 2021). "In this study, we found that sepsis induced more double-membrane autophagosomes, the shift from LC3-I to LC3-II, increased levels of beclin-1 and Atg-5, and reduction in free p62 in the mouse hippocampus, indicating the activation of hippocampal autophagy." (PMID 34711216, 2021). "A comparative analysis was performed with respect to the mRNA expression of ATG5 and ATG16L1 in the PBMCs of 80 sepsis cases and 80 controls." (PMID 28839236, 2017). "Second, in this study only five ATG5 and ATG16L1 genetic polymorphisms implicated in the susceptibility and progression of sepsis were examined, whereas other polymorphisms of ATG5/ATG16L1 and other autophagy-related genes that may be associated with sepsis remained to be identified." (PMID 28839236, 2017). "Apart from these proteins, expression of ATG12 was found to be increased in sepsis (p = 0.047), though another autophagy gene ATG5 was increased but not significant in sepsis." (PMID 35681439, 2022). "For example, in the cecal ligation puncture (CLP)–-induced sepsis mice model, the levels of LC3-II, ATG5, and ATG7 are downregulated in the lung of mice with sepsis, suggesting that sepsis may suppress autophagy." (PMID 30717487, 2019). "HIPK2 overexpression reduced the sepsis-mediated increase in calpain 1 and cleaved Atg5 levels but did not affect mTOR levels." (PMID 30154452, 2018). "Our results showed that the ATG5 and ATG16L1 expression levels in the sepsis cases were significantly reduced relative to the controls (P < 0.001), and it is worth nothing that the ATG5 and ATG16L1 mRNA expression levels decreased significantly with the aggravation of sepsis (P < 0.05)." (PMID 28839236, 2017). "Our results showed that ATG5 and ATG16L1 expression levels in sepsis patients were significantly reduced relative to healthy controls, and that it decreased with the aggravation of sepsis which was consistent with these previous studies." (PMID 28839236, 2017). "All samples were sequenced and genotyped successfully and no deviations from Hardy-Weinberge quilibrium were observed for these ATG5 and ATG16L1 polymorphisms in sepsis and control groups (all P > 0.05, data not shown)." (PMID 28839236, 2017). "The upregulation of LC3B-II, Atg5, and Beclin-1 proteins in the Tg mice without sepsis suggests that IκBβ* affects the expression of Autophagy Related genes (Atgs)." (PMID 27508931, 2016). "We found significant differential expression of LC3B-II, Atg5, and Beclin-1 between WT and Tg mice with or without sepsis." (PMID 27508931, 2016). "In our study, we used T cell–specific Atg5 knockout mice (CD4-Cre recombinase/Atg5f/f mice: CD4-Cre/Atg5f/f mice) and performed a CLP procedure to prove our hypothesis that autophagy is related to apoptosis in sepsis." (PMID 27618275, 2017). "Although Beclin1, Atg7, and Atg12 in the Sepsis group were all slightly higher than the SFP group (p < 0.05), Unc-51-like autophagy activating kinase (Ulk1), Atg5, Atg8l, and Lamp2 were not different." (PMID 37106730, 2023). "The expression levels of ATG5 and ATG16L1 in the 28-day non-surviving patients with sepsis were significantly decreased compared to the 28-day surviving patients (P < 0.01)." (PMID 28839236, 2017).
cervical carcinoma (12 papers, 2012 to 2025). A carcinoma arising from either the exocervical squamous epithelium or the endocervical glandular epithelium. "Eight methylation sites of ATG5, namely, four sites with good prognosis and four sites with poor prognosis, were explored to be significantly associated with OS of cervical cancer patients." (PMID 34901004, 2021). "TCGA CESC methylation data showed that eight methylation sites of ATG5 could also be significantly associated with the overall survival (OS) of cervical cancer patients." (PMID 34901004, 2021). "ATG5 mRNA showed higher expression in cervical cancer cell lines Hela and Ca Ski compared with the cervical epithelial cell line CRL2614." (PMID 34901004, 2021). "It was vital that ATG5 was the only important harmful marker influencing the prognosis of cervical cancer patients." (PMID 34901004, 2021). "In brief, these results exhibited the repression of ATG5 in the migration and invasion of cervical cancer cells in vitro." (PMID 34901004, 2021). "Regardless of stage, grade, and pathological characteristics, cervical cancer patients with high expression of ATG5 had shorter survival." (PMID 34901004, 2021). "Next, cell migration and invasion assay and Western blot were applied to detect the function of ATG5 in EMT of cervical cancer." (PMID 34901004, 2021). "We found that a high level of ATG5 expression was an important poor prognostic factor in cervical cancer." (PMID 34901004, 2021). "To investigate the link between autophagy blockade and cell death induced by TBM, we transfected cervical cancer cells with Beclin1 or ATG5 siRNA, followed by TBM treatment." (PMID 30389907, 2018). "Likewise, the data of the Transwell invasion assay showed that downregulation of ATG5 dramatically suppressed the invasion in cervical cancer cells." (PMID 34901004, 2021). "In addition, cervical cancer cell lines were used to investigate the effect of ATG5 on migration and invasion." (PMID 34901004, 2021). "Generally, downregulation of ATG5 could reverse the EMT process by specific pathways in cervical cancer cells and resulted in attenuation of migration and invasion." (PMID 34901004, 2021). "In addition, further studies were performed to verify the role and the potential mechanisms of ATG5 in promoting migration and invasion in cervical cancer cell lines." (PMID 34901004, 2021). "In cervical cancer cells, ATG5 knockdown resulted in attenuation of migration and invasion." (PMID 34901004, 2021). "Our results suggested that ATG5 acted as a poor prognostic marker and may be applied as a potential target for reversing the invasion and metastasis in cervical cancer." (PMID 34901004, 2021). "Furthermore, molecularly inhibiting autophagy by transfecting cervical cancer cells with ATG5 or Beclin1 siRNA decreased the LC3 II expression." (PMID 30389907, 2018). "In summary, ATG5 involved in the EMT process and immune regulation in cervical cancer could affect the survival of cervical cancer patients by expression and methylation level, proposing that ATG5 may be a potentially powerful therapeutic target for cervical cancer." (PMID 34901004, 2021). "ATG5 knockdown could inhibit migration and invasion of cervical cancer cells by reversing EMT." (PMID 34901004, 2021). "DARS-AS1/DARS can regulate the expression of ATG5 via m6A modification mediated by METTL3/14, indicating the development of autophagy in cervical cancer cells." (PMID 39468015, 2024). "In conclusion, the present study implies that ATG5 was a major contributor to EMT regulation and poor prognosis in cervical cancer." (PMID 34901004, 2021). "The pro-autophagic effects of ursolic acid in the suppression of TC-1 cervical cancer cells and NSCLC cells have been reported to be mediated by LC3-II and ATG5, depending on the concentration." (PMID 34575981, 2021). "Our results suggested that ATG5, as one of ARG signatures, was an essential contributor to the poor prognosis of cervical cancer." (PMID 34901004, 2021).
cervical carcinoma (continued). "In addition, our analysis about genomic alterations and methylation of ATG5 showed the concomitant occurrence of ATG5 mutation and ULK2 mutation and indicated that methylation sites of ATG5 could also serve as prognosis predictors in cervical cancer patients." (PMID 34901004, 2021). "RAME treatment increased the mRNA levels of ATG genes (ULK1, ATG5, BECN1, ATG7, ATG12, and ATG13) dose dependently in cervical cancer cells." (PMID 31387554, 2019). "We analyzed the relationship between ATG5 and EMT-related gene signature in cervical cancer." (PMID 34901004, 2021). "However, the effect of ATG5 on EMT and the prognosis in cervical cancer is unknown to date." (PMID 34901004, 2021).